CD4 (CD4 molecule)
Diseases named in the same sentence as CD4 in open-access papers (continued):
Sharing a sentence is not in itself a finding about the gene and the disease.
tumor (continued). "To further characterize T-cell subtypes in the Paediatric Inflamed cluster with high levels of lymphocyte infiltration, we obtained 40 gene signatures of CD4 + and CD8 + T-cell subpopulations from the single-cell profiling of tumour-infiltrating lymphocytes." (PMID 37679810, 2023). "The bona fide candidate genes CD8A, CD4, and CD274 showed increased expression in T cells and tumor cells, respectively." (PMID 36672341, 2023). "Further prospective studies with specific tumor type and detailed analysis of lymphocyte subgroups (such as CD3+, CD4+, CD8+, NK cells, B cells, etc.)are needed." (PMID 37070077, 2023). "CXCL10 and CCL5 chemokines were reported to stimulate CD4+ and CD8+ lymphocyte migration into the intra-tumor and stromal compartment, and CCL20 drove brain infiltration of Treg cells." (PMID 38239560, 2023). "In particular, we distinguish the tumor-specific immune abilities of CD8+ T, NK cells, and CD4+ T cells and describe the destructive ability of cytokine on tumor cells as well as the inhibitory capacity of CTLA-4 on various components." (PMID 36766849, 2023). "Our study demonstrated that oxamate reduced the number of tumor-infiltrating Treg cells through inhibiting CCR8 expression, lactate increased CCR8 expression in cultured CD4 + T cells in vitro." (PMID 37770937, 2023). "Moreover, trastuzumab could enhance the efficacy of immune checkpoint inhibitors through increasing HER2 internalization and cross-presentation by dendritic cells, upregulating PD-1 and PD-L1 expression, inducing the expansion of tumor-specific CD4 and CD8 T cells and MHC class II expression." (PMID 37274273, 2023). "High beta-2 microglobulin (B2M), LAG-3, CD25, and 4-1BB in tumor; high B2M, CD45, CD4 in stroma, and low fibronectin in the macrophage compartment, correlated with prolonged PFS." (PMID 37057033, 2023). "Intranasal delivery of CCL2 to BALB/c mice markedly enhanced the seeding and outgrowth of 67NR cells in the lung and increased the recruitment of CD4+ T cells and CD8+ central memory T cells into the lungs of tumor-bearing mice." (PMID 37208442, 2023). "We enrolled 89 patients with NCT‐NSCLC in this study; the tumor‐infiltrating lymphocyte (TIL), CD4+TIL, and CD8+TIL levels in naïve and post‐chemotherapy tumor tissues were detected using immunohistochemistry staining and divided into high and low groups." (PMID 36789099, 2023). "CD4+ T cells and CD8+ T cells isolated from WT mice were adoptively transferred to RWT and RKO mice on Day 12 of tumor implantation." (PMID 38071226, 2023). "The expression of NDC1 is generally associated with the high expression of T cells follicular helper, Neutrophils, T cells CD4 memory activated and the low expression of T cells CD8, NK cells activated and Monocytes in 33 tumor types." (PMID 37733696, 2023). "Analysis of the lymphocyte interactome from both treatments revealed increased tumor interactions of CD8+ T cells, NK cells, and to a lesser extent CD4+ T cells and Tregs, compared to negligible interactions among γδ T cells, NKT Cells, ILCs, and B cells." (PMID 37871202, 2023). "CD8+ and CD4+ T cells recognizing HPV E6 and E7, as well as other HPV proteins, have been identified in both the peripheral blood and tumor-infiltrating lymphocytes (TILs) from patients with HPV-associated cancers." (PMID 36512410, 2023). "Activated MDSCs induce the inactivation of NK cells, CD4+, and CD8+ T cells through a variety of mechanisms, thus promoting the formation of tumor immunosuppressive microenvironment." (PMID 36593497, 2023). "Some studies have revealed that an increased number of CD4+ helper T cells, and CD8+ cytotoxic T cells, known as tumor-infiltrating lymphocytes (TILs) are positively correlated with a favorable prognosis in patients with PDAC." (PMID 37477731, 2023).
tumor (continued). "We next analyzed tumor-infiltrating lymphocytes via flow cytometric analysis and found that FGL1 depletion enhanced the infiltration of IFN-γ+ CD8+/CD4+ and Ki67+ CD8+/CD4+ T cells within the tumor microenvironment." (PMID 37872170, 2023). "Whilst several studies have shown the importance of CD4+ T-cell subsets, translational research in phase II ICI trials has yet to show their exact role in anti-tumour responses." (PMID 37958391, 2023). "The present study shows that the spatial distribution of CD4+, CD8+, CD68+, and CD163+ immune cells differs between the tumor center and invasion front of OSCC." (PMID 36836239, 2023). "Even so, clinical reports of abscopal effects have been reported, and benchtop research has demonstrated increased tumor-specific T cell populations in HCC, as well as increased B-cell/CD4+ interactions in breast cancer." (PMID 36969248, 2023). "By eradicating tumor cells directly through cytolytic mechanisms or modulating the TME indirectly, CD4 + T cells can target tumor cells in various ways." (PMID 37741993, 2023). "As the data indicate, the vaccination in the presence of markedly reduced CD4+ and CD8+ T cells provided 100% protection against tumor development induced by a very virulent strain of MDV." (PMID 36992357, 2023). "Tumor killing by immune cells is generally ascribed to CD8+ CTL, while CD4+ T cells have been traditionally thought to function in cytokine production and to help CD8+ CTL exert cytotoxic functions." (PMID 36765793, 2023). "It has been shown that MDSCs can potently suppress tumor immunity by directly acting on CD8 and CD4 T lymphocytes as well as NK cells." (PMID 37207205, 2023). "This admixture of cells predominantly consists of polyclonal, mostly tumor-specific CD8+ and CD4+ T cells which can bind to multiple TAAs and overcome the tumor heterogeneity and antigen escape." (PMID 37509394, 2023). "Specifically, 5-HT1aR on T cells is critical for expanding the group of CD4(+)CD25(+)Foxp3(+) Treg cells and reducing the ratio of Th1/Th2 cells, and 5-HT1aR on tumor cells is inversely related to cytotoxic lymphocytes activity." (PMID 37215113, 2023). "This presents a physical barrier to T lymphocyte penetration of the tumor, with one study finding an inverse correlation between CD31+ vessel density and both CD4+ and CD8+ T lymphocytes in cholangiocarcinoma." (PMID 37444422, 2023). "TheraVacplus treatment elevated levels of effector/memory CD4 and CD8 T cells in tumor tissue and draining lymph nodes and generated activated CD8+ T cells when cocultured with 4T1 cancer cells." (PMID 37190294, 2023). "The ranking of the APC-binding molecules tested in the second experiment based on improved tumor control, and induction of reactive CD8+ and CD4+ T cells, pointed to CCL19_Neo5 as the most efficient APC-targeting construct." (PMID 37720215, 2023). "The baseline CD4+, CD8+ T cells, and their PD-1-positive-expressed subsets were mostly located within the 100-μm distance to tumor cells." (PMID 37275884, 2023). "The 2-HG is secreted by tumor cells and imported by CD8+ T cytotoxic and CD4+ T helper cells by a sodium-dependent dicarboxylate transport system and inhibits TCR by interfering with the TCR—ATP dependent signaling and a polyamine biosynthesis pathway." (PMID 36831383, 2023). "During immunotherapy, expressing HLA class II activates CD4+ T-cell, which help to initiate CD8+ T-cell and mount a successful anti-tumor immune response." (PMID 37091977, 2023). "It was found that M2 macrophages, CAFs, and some T lymphocytes were always located in the center of the tumor, and these T lymphocytes were identified as exhausted CD8+T cells and unconventional CD4+T cells." (PMID 36459212, 2023). "In line with the TIL assessment, we confirmed similar frequencies of tumor-infiltrating T cells, such as total CD3+ cells, conventional CD4+ T conventional (Tconv) cells, CD4+ Tregs and CD8+ T cells in PF and PD patients." (PMID 37349318, 2023).
tumor (continued). "We also observed significant increases in the percentage of CD4+ and CD8+ T cells in the spleens of 4T1 tumor–bearing mice following alprazolam treatment." (PMID 37847562, 2023). "Immune stimulation potential confirmed the increased percentage of T-cells population in the tumor, and the population of effector T-cells, IFN-γ+ CD4+, and IFN-γ+ CD8+ T-cells, was also increased." (PMID 37835397, 2023). "Together, these observations indicated that CD4+ T cells can interact with MHC-II+ immune and tumour cells at the invasive margin, whereas CD8+ T cells predominantly interact with MHC-I+ tumour cells." (PMID 37316667, 2023). "Together, these data indicate that both CD4+ and CD8+ T-cell subsets take part in mediating the anti-tumor effect and shaping the immune response of neoepitope DNA vaccination." (PMID 37244905, 2023). "CD4+T cells, CAF, MDSC, neutrophils and macrophages have been shown to play key roles in tumor immunotherapy." (PMID 36961395, 2023). "The presence of tumor-infiltrating lymphocytes (TIL), such as CD8+ and CD4+ T cells and natural killer (NK) cells, are known to correlate with favorable outcomes." (PMID 36673082, 2023). "On the contrary, the tumor of Lv-ISG15 groups, Ki67 and CD31 staining were weak, and numbers of CD3+, CD4+ and CD8+ tumor-infiltrating lymphocytes were significantly reduced." (PMID 37217923, 2023). "CD4+ cells and CD8+ T cell types are required for proper tumor suppression, as CD8+ cells (cytotoxic T cells or CTL) need CD4+ cells (helper T cells or TH) for correct activation." (PMID 37240369, 2023). "In contrast to CD4+ TILs, the composition of PD-1 and TIM-3 subsets within CD8+ TILs changed over the course of tumour outgrowth." (PMID 37153625, 2023). "This suggests that beyond the short-term tumor elimination mediated by CD8+ T cells, CD4+ T cells contribute to long-term remission." (PMID 37970489, 2023). "A comparison of the proportions of CD3+, CD4+, CD8+, and CD4+Treg+ cells in PBMC, TDLN, and tumor revealed that TDLN was skewed toward either PBMC or the tumor, depending on which subset one looks at." (PMID 37444407, 2023). "Here, viral DNAs in the cytosol activated cGAS and downstream activated STING, IRF3, IRF7, IFN gene expression, and tumor death through the generation of antitumor CD8+ and CD4+ effectors in murine models." (PMID 38139802, 2023). "TILs are the major component of the tumor microenvironment and consist of CD3+ CD4+ (helper) and CD3+ CD8+ (cytotoxic) T cells." (PMID 36614308, 2023). "HOX-SI subtype had a higher abundance of most types of tumor-infiltrating immune cells than HOX-SII, including CD4 memory resting T cells, monocytes, M2 macrophages, resting mast cells, and neutrophils." (PMID 37547473, 2023). "To evaluate the contribution of either CD4+ or CD8+ T cells in the anti–PD-1/CTLA-4 combination, we tested the in vivo effects of CD4+ and/or CD8+ T cell depletion on syngeneic tumor growth." (PMID 37449205, 2023). "The favorable involvement of CD4+ T regulatory cells and the unfavorable involvement of CD163+ TAMs and CD73+ tumor cells were also presented to correlate with the pCR rate." (PMID 36769287, 2023). "Strikingly, we found increased IFN-γ+ and double-positive IFN-γ+ and TNF-α+ tumor-infiltrating CD8+ and CD4+ T cells in tumors with B7-H3 knockdown compared with controls." (PMID 36869048, 2023). "In contrast, PD-1 expression decreased in both REP TIL CD4+ (18.8%) and CD8+ T cells (14%) compared with the pre-REP TILs (28% and 21.4%) and tumors (41.6% and 54%), indicating that T cells residing in the tumor encompassed the greatest amount of exhaustion." (PMID 37484198, 2023).
tumor (continued). "The number of unique high-frequency anti-tumor memory TRB clonotypes in the peritoneum varied from 1 to 8 in CD4 and 4-8 in CD8 T-cells with a median of 4 CD4 T-cells and 6 CD8 T-cells." (PMID 37033929, 2023). "Compared with the control group, the H22 vaccine group induced an increased number of CD4+CD8+CD19+ T cells and significantly inhibited tumor growth." (PMID 38004595, 2023). "Five parameters were identified in univariate Cox analysis as prognostic factors for RFS (p < 0.05): CD3 density measured in the tumor or at the invasion margin, CD8+ CD226high T cells, CD4+ CD226high T cells, and CD4+ TIGIThigh T cells." (PMID 36717657, 2023). "The infiltrating immune cells, such as B cells, CD4+ T cells, CD8+ T cells, macrophages, and neutrophils, secreted a variety of factors that affected TME and regulated tumor behavior and anti-cancer capacity." (PMID 38147021, 2023). "The major subsets of tumor infiltrating lymphocytes (TILs) include CD3+, CD8+, CD4+, and FOXP3+ cells." (PMID 37537787, 2023). "Pancreatic stellate cells in PAAD can secrete CXCL10, which can recruit CXCR3+CD4+ cells, CXCR3+CD8+ cells and CXCR3+ Tregs into tumor tissue." (PMID 36782176, 2023). "On the side of anti-tumor activity, CD4, CD8, and NK cells as well as DC can build effective immune responses against a tumor." (PMID 37810959, 2023). "T-cells, including CD4+, CD8+, and NK cells, also play an essential role in resisting tumour development." (PMID 37853210, 2023). "The immune landscape of the TH-MYCN tumour following JQ1 treatment showed an increased percentage of CD8+PD-1+, CD4+PD-1+, and Treg PD-1+ cells compared to controls, although it did not affect immune cell infiltration to the TME." (PMID 37887559, 2023). "Higher densities of CD3+, CD4+ and CD8+ cells were also localised to the outer tumour region compared to the inner tumour core." (PMID 37153625, 2023). "In this study, we investigated the capacity of CD4+ T cells specific for the oncoproteins HPV-16 E6 and KRASG12V to recognize antigen-expressing tumor cells." (PMID 36512410, 2023). "Further analysis revealed the lower ratio of CD8+ to CD4+ T cells in INT than that in TB, suggesting fewer cytotoxic cells existing inside tumors than at tumor border." (PMID 37353792, 2023). "CD8+ T cells are the major cell type mediating anti-tumor effects, and the CD8+/CD4+ ratio indicates the amount of CD8+ T cells of specific anti-tumor immunity." (PMID 37426671, 2023). "In tumor cell-enriched regions, PDCD1 expression was negatively correlated with the levels of monocytes and CD4+ memory-activated T cells." (PMID 37151882, 2023). "The presence of CD4+ and CD8+ lymphocytes at the tumor site in melanoma and non-small cell lung cancer has been reported to have good prognostic significance for the OS." (PMID 38203530, 2023). "Another interesting finding was that CD4+ CTLs expressed B cell-attracting chemokine CXCL13, thereby inducing B cell migration to tumor lesions." (PMID 38077321, 2023). "The result indicates that CD8+ T‐cells tended to focus on tumor core (DAPI‐dense), by contrast, CD4+ T‐cells tended to evenly infiltrate in normal tissue (DAPI‐sparse) and tumor regions in NE(PD1nb) group." (PMID 37565362, 2023). "In contrast, the high-risk group had a diverse TIM with high concentrations of immune cells that promote tumor growth, such as Tregs and Th2, as well as immunological cells like natural killer (NK) cells and CD4/CD8 T cells, which halt tumor development." (PMID 38162504, 2023). "IHC staining of the secondary tumours revealed cryoablation promoted the infiltration of CD4+ and CD8+ T cells into the tumours." (PMID 37157934, 2023). "Subsequently, dendritic cells migrate to nearby lymph nodes, presenting tumor antigens and activating tumor-specific CD4+ and CD8+ T cells, which then migrate to the tumor site to kill the cancer cells." (PMID 37818195, 2023).
tumor (continued). "Following NK cells therapy, higher proportions of CD3 + CD4 + T lymphocytes, CD3 + CD8 + T lymphocytes, and DCs were confirmed in the splenocytes of MB49 tumor-bearing mice." (PMID 37253929, 2023). "As a result, DCs and antitumor CD4+ and CD8+ T cells were observed to accumulate in Huaier-treated 4T1 breast cancer-bearing mice, together with restrained tumor growth and improved general conditions." (PMID 37449208, 2023). "We found that the infiltration levels of immunocytes that inhibited tumour progression, such as CD8+ T cells, CD4+ T cells, activated NK cells and M1 macrophages were much lower in the high‐PHF6 patients than in the low‐PHF6 patients." (PMID 36756714, 2023). "We applied ST technology to assess the spatial locations of Prol Epi, Prol CD4+ T, and Prol CD8+ T, and found that Prol Epi, Prol CD4+ T, and Prol CD8+ T GSVA scores were all higher in the same tumor area." (PMID 37601684, 2023). "Tumor cells showed the typical morphology and phenotype (CD30+, ALK-, PAX5-, EBER-) with all but one being CD3-negative and all but one expressing CD4 (at least focally)." (PMID 37555981, 2023). "Elevated levels of TGF-β can inhibit anti-tumour immunity by activating SMADs and NFAT to induce the expression of FOXP3 in CD4+ T cells, which can promote their differentiation to a Treg phenotype." (PMID 38259489, 2023). "However, CD4+ T cells from the tumor-bearing and anti-IL-6 treatment alone groups reduced the cytotoxicity of the corresponding CD8+ T cells, which further demonstrated that CD4+ T cells from combination therapy could enhance the cytotoxic function of CD8+ T cells." (PMID 37108179, 2023). "We found the expression of STARD12 was positively correlated with the abundance of infiltrating immune cells, including B cells, and CD4+ T cells, CD8+T cells, macrophages, and dendritic cells, which enhanced the anti-tumor immune response." (PMID 37790851, 2023). "Infiltration by TCM (CD44HICD62L+) CD4+ and CD8+ subsets was consistently low throughout tumour outgrowth (>13% and >20% of total CD4+ and CD8+ TILs, respectively)." (PMID 37153625, 2023). "Conventional T cells consist of CD8 + and CD4 + T cells, and the former outnumber the latter in the liver; CD8 + T cells are the main tumor-infiltrating lymphocytes that perform anti-tumor functions." (PMID 36773210, 2023). "LAG3 expression is significantly higher on CD4+ and CD8+ tumor-infiltrating lymphocytes (TILs) than in other immune constituents among HCC patients." (PMID 36845131, 2023). "Of note, the averaged CD163+ TAM counts correlate positively with the patient’s age and negatively with CD3+, CD4+, and CD8+ lymphocyte counts within the tumor." (PMID 38136307, 2023). "Metaclusters were next parsed by frequency of CD4+ T cells or CD8+ T cells among treatments in TIL, spleen, and tumor-draining Ig LN." (PMID 37655661, 2023). "Dendritic cell presentation of tumor antigens to CD4+ and CD8+ T-lymphocytes is critical for tumor immunity, and CD86 has also been found to be a biomarker for a variety of tumor immune-related prognoses." (PMID 36674743, 2023). "The tumor of the WT groups, positive staining of cell proliferation marker Ki67 and angiogenesis marker CD31 were found to increase, and the number of CD3+, CD4+ and CD8+ tumor-infiltrating lymphocytes were significantly reduced." (PMID 37217923, 2023). "Using our protein/RNA-based method and a panel of 11 markers we identify 14 different immune subtypes, including activated CD4+ and CD8+ T-cells, macrophages and B cells present within the inner tumor." (PMID 37704757, 2023). "In the tumor microenvironment (TME) of HNSCC in biologically old patients, lower numbers of CD163+ (type 2 or M2) macrophages, CD4+ and CD8+ lymphocytes were found." (PMID 37568649, 2023). "TAC consists of 3 components: a tumor antigen binding domain, a CD3 binding domain which interacts with and co-opts the native TCR and a CD4 co-receptor transmembrane and intracellular domain." (PMID 38274800, 2023).